HIF1A (hypoxia inducible factor 1 subunit alpha)
Diseases named in the same sentence as HIF1A in open-access papers (continued):
Sharing a sentence is not in itself a finding about the gene and the disease.
tumor (continued). "However, tumor infiltrating MDSCs polarized toward TAM by CSF-1 and HIF-1α." (PMID 33062602, 2020). "Given the paucity of evidence supporting mutations of the PKA subunits as being causative of GH hypersecretion in sporadic cases, our study presents a novel nongenomic mechanism through which HIF-1α acts as a surrogate of the tumor microenvironment to influence GH synthesis." (PMID 32111982, 2020). "The IF results demonstrated that the expression of HIF-1α, VEGF, and CD 31 was significantly downregulated in eMIONs group and was much lower in eMIONs + AMF group compared with the other groups, showing that the catalytic effect changed the tumor microenvironment to inhibit angiogenesis." (PMID 33110072, 2020). "In this study the absence of HIF1a and endogenous androgen in vivo resulted in regression of tumor growth but HIF1a signaling could restore tumor growth in the absence of AR signaling." (PMID 32450824, 2020). "Here, we assume that HIF1A is produced by both tumor and non-tumor cells at the microenvironment, contributing to this immune cell recruitment, but it will be important to determine which population is the main contributor to pursue possible therapeutic applications." (PMID 32231135, 2020). "Among the 108 patients with tumor metastasis, 56 patients (51.8%) had high expression of both HIF-1α and SP1, 12 patients (11.1%) had high expression of HIF-1α, 13 patients (12.0%) had high expression of SP1, and 27 patients (25.0%) patients had low expression of both HIF-1α and SP1." (PMID 31892989, 2020). "During neoplastic progression, tumour cells generate mechanisms to survive the negative effects of hypoxia, one of which is the activation and stabilisation of the transcriptional activity of HIF-1α, which can then regulate the NOTCH1 signalling pathway." (PMID 32386517, 2020). "CRLX101, a HIF-1α expression inhibitor, has completed a phase II trial in combination with bevacizumab, an antibody that targets VEGF, for the treatment of recurrent platinum-resistance ovarian, tubal, and primary peritoneal cancers and reduce tumor frequency and size." (PMID 33113858, 2020). "Some studies demonstrated a significant accumulation of HIF-1α or β in IDH1mut cell lines, while others obtained contrasting results when examining the effect of 2-HG accumulation on HIF1 induction/stabilization and/or hypoxia gene signatures activation in different tumor types and in vivo models." (PMID 32824685, 2020). "Among these, HIF-1α (hypoxia-inducible factor-1 alpha) induces the expression of BNIP3/BNIP3L (atypical BH3-only proteins the Bcl-2/E1B 19 kDa-interacting protein 3) that, in turn, favors the dissociation of Bcl-2-Beclin1 complexes, activates autophagy and promotes tumor progression." (PMID 33020404, 2020). "Therefore, we detected the expression of hypoxia-inducible factor 1α (HIF-1α), tyrosine-protein kinase receptor UFO (AXL) mRNA, and vascular endothelial growth factor (VEGF) mRNA to observe the effect of TNuF on the angiogenic pathway in tumor cells." (PMID 32872195, 2020). "Thus, HIF-2a is an attractive target since moderate hypoxia induces HIF-2a exclusively in CSCs, while HIF-1a is induced in both CSCs and non-stem tumor cells." (PMID 32566921, 2020). "In addition, hypoxia-inducible factor 1α (HIF-1α) and vascular endothelial growth factor (VEGF) are activated by CTHRC1 through activating the PI3K/AKT/mammalian target of rapamycin (mTOR) signaling pathway, which promotes tumor angiogenesis." (PMID 32848510, 2020). "Under conditions of reduced O2 concentrations, HIF-1α (the subunit of HIF heterodimer oxygen-sensitive) binds to the elements responsive to hypoxia (HREs) and induces the transcription of various target genes involved in tumor angiogenesis, glucose metabolism, invasiveness and cell survival." (PMID 32131421, 2020).
tumor (continued). "Reduction in HIF-1α and expression of angiogenic factors (FGF2, PDGF-AA, CYR61, and VEGF) and subsequently intratumor hypoxia is due to the ability of Infigratinib/Bevacizumab to increase tumor oxygen supply via Infigratinib-induced vascular normalization of tumor blood vessels." (PMID 33321903, 2020). "Therefore, collectively these data suggest that NLGP does not affect HIF1α expression in either protein or mRNA level at 4 h to control their VEGF production in tumor cells." (PMID 32211322, 2020). "Several studies have demonstrated that the hypoxia inducible factor-1alpha (HIF-1α) stabilization, favored by the hypoxic MM BM niche, induces the transcription of a few pro-angiogenic factors, including Vascular Endothelial Growth Factor A (VEGF-A), both in tumor and stromal cells." (PMID 33489901, 2020). "Furthermore, PTBP1 binds the 5′ UTR internal ribosome entry site in HIF1α mRNA, enhancing HIF1α translation, and accounts for 40–50% of hypoxia-stabilized HIF1α levels, increasing the influence of hypoxia-induced LUCAT1/PTBP1 complexing on tumour suppressor inactivation through alternative splicing." (PMID 32536347, 2020). "Furthermore, they significantly inhibited the hypoxia-induced HIF-1α accumulation and VEGF production in HCC cells, suggesting that the α-mangostin glycosides may inhibit tumor angiogenesis of HCC through the downregulation of HIF-1α and its target gene, VEGF." (PMID 32516967, 2020). "This could subsequently lead to inhibition of HIF-1α/VEGF axis and VEGF secretion by tumor cells." (PMID 33424993, 2020). "In addition, hypoxia-induced HIF-1α activated the expression of glucose transporter-1 (GLUT-1), which conferred the enhanced tumor antioxidant capacity linking to radioresistance through initiating a glycolytic tumor metabolism." (PMID 32403326, 2020). "A further corollary of our findings is that inhibition of HIF-1α and HIF-2α transcription factor activities in ccRCC cells could be investigated therapeutically to inhibit tumour cell proliferation and simultaneously to attempt to increase T-cell infiltration and activation." (PMID 32807776, 2020). "However, it is unclear whether there is a specific interaction between HIF-1α and SP1 promoter in tumor cells." (PMID 31892989, 2020). "Studies of HIF-1α and SP1 in tumor metastasis are rare and related mechanisms remain unclear." (PMID 31892989, 2020). "Furthermore, HIF-1α knockdown did not affect the growth of allograft tumours generated with this ccRCC cell line." (PMID 32807776, 2020). "The cytoplasmic and nuclear accumulation of NRF2 occurs only in tumor cells and not in stroma and starts in the early stages of the disease, probably supporting the malignant transformation of cysts, whose formation is independent of HIF-1α." (PMID 33233657, 2020). "Therefore, there were definitive cross-talks between HIF-1α and other EMT signaling pathways yet the relationship could be tumor-type and context-dependent." (PMID 32322559, 2020). "Therefore, tumor angiogenesis is sustained by galectins via autocrine and paracrine mechanisms as well as by direct interactions with VEGFR2 and HIF1α." (PMID 32974337, 2020). "It was found long-term hypoxic tumors are not sensitive to TRAIL treatment and that inhibition of HIF-1α expression increases tumor sensitivity to TRAIL and promotes apoptosis, suggesting that HIF-1α may regulate apoptosis through the TRAIL pathway." (PMID 32848609, 2020). "However, there is yet no proof of Nur77/HIF-1α involvement in the process of LNT-mediated tumor-inhibition effect." (PMID 33245358, 2020). "In addition, we detected the protein expressions of CHCHD2 and HIF-1a in tumor tissues and adjacent non-cancerous tissues by immunohistochemistry in specimens from 209 patients." (PMID 32054470, 2020).
tumor (continued). "Therefore, we investigated the therapeutic potential of isoform-specific HIF-1α and HIF-2α antisense oligonucleotides (ASOs), along with their effect on the inflammatory and fibrotic component of the tumor microenvironment (TME), in an experimental HCC mouse model." (PMID 33400730, 2020). "SIRT3 down-regulates HIF1α and pyruvate dehydrogenase kinase 1 (PDK1) in cholangiocarcinoma, and suppresses the Warburg effect also by the activation of pyruvate dehydrogenase complex (PDC) and the indirect inhibition of the tumor specific isoenzyme hexokinase II (HK II)." (PMID 32117717, 2020). "Accordingly, in this study, we hypothesized that in a tumor microenvironment, RT-R-MDA-MB-231 cells, which contain more CSCs than MDA-MB-231 cells, induce HIF-1α expression and LOX secretion, and then finally premetastatic niche formation, more than MDA-MB-231 cells do." (PMID 33126606, 2020). "That the effects of hypoxia and HIF-1α on therapy resistance and survival at least in part is in cross-talk with EGFR opens for new application of established EGFR-inhibitors as well as for emerging HIF-inhibitors combined with strategies to minimize tumor hypoxia." (PMID 31821370, 2019). "Interestingly, our results showed that YY1 inhibition of PGC-1β expression occurs independent of hypoxia-inducible factor-1α (HIF-1α), a key regulator of hypoxic response that has been known to promote tumor cell lipid accumulation." (PMID 31695789, 2019). "In addition, HIF1A promotes autophagy by altering the expression of BCL2/adenovirus E1B 19 kDa protein-interacting protein 3 (BNIP3), which is part of a stress adaptation mechanism that promotes tumor cell survival and avoids cell death." (PMID 31744467, 2019). "Therefore, we stained and compared HIF1A and VEGFA in these tumor tissues." (PMID 31312613, 2019). "Furthermore, HIF-1α induces the expression and secretion of soluble molecules such as VEGF, which, besides their proangiogenic role, have a chemoattractant function for myeloid cells, or endothelins by tumor cells." (PMID 30708988, 2019). "The quantitative results showed that the expression of HIF-1α in the PNP group was almost 2 times as much as that in the ONP group, indicating that PNPs could create and maintain long-term tumour hypoxia for at least 24 h in vivo." (PMID 30952842, 2019). "However, the proportion of sections containing tumours, consistent with overall tumour burden, is lower in animals lacking endothelial HIF-1α in all pre-treatments, especially after acute hypoxia." (PMID 31308473, 2019). "HIF-1α is a master regulator of the adaptive response to hypoxia that induces the transcription of genes such as vascular endothelial growth factor (VEGF), lysyl oxidase (LOX), GLUT1, and PDK1, which sustain vascularisation, metastasis, and tumour cell survival." (PMID 31052256, 2019). "However, these and additional pathways relating to metabolic reprogramming, via, for example, Wnt and HIF1α-, are important also in non-TIC tumor cells, and include pathways associated with epithelial–mesenchymal transition (EMT)." (PMID 31661927, 2019). "In response to hypoxic conditions, tumor cells reprogram protooncogenes (e.g., cellular myelocytomatosis oncogene (c-Myc)), modify signaling pathways (e.g., Phosphoinositide 3-kinase (PI3K/Akt), and activate specific transcription factors (e.g., hypoxia-inducible factor 1 alpha, HIF-1α)." (PMID 31905745, 2019). "Therefore, HIF-1α failed to bind the hypoxia response element of the initiator, leading to downregulation of target genes relevant to tumor metastasis and VM formation." (PMID 31022939, 2019).
tumor (continued). "Therefore, HIF-1α expression in NK cells in hypoxic environments may inhibit VEGF, which then promotes productive angiogenesis and tumor growth." (PMID 31396523, 2019). "Of note, Ad E1A was detected in the normoxic regions of d19-, a2bm-d19-, or Ha2bm-d19-treated tumors, whereas only Ha2bm-d19 was detected in abundance within the hypoxic tumor region (HIF-1α-positive) with no spots being observed for d19- or a2bm-d19-treated tumors." (PMID 29396500, 2018). "However, in contrast to our finding, in mice injected with A549 cells, silencing HIF-1α impaired tumor vascularization and increased the necrotic area, but did not reduce tumor cell proliferation and only slightly impacted tumor growth." (PMID 30250643, 2018). "In addition, tumour sections were co-labelled for CSRP2 and HIF-1α." (PMID 29976963, 2018). "As the glycolytic phenotype of tumor cell is triggered mainly by HIF-1α master regulator, we sought to find out, whether the drugs may exert its effect on metabolic reprogramming of HTB-35 cell via HIF-1α and its downstream proteins." (PMID 29958416, 2018). "Since therapeutic doses and the schedule of selenium partially downregulate the expression levels of VEGF in tumor cells expressing HIF1α but not HIF2α, we propose, therefore, adding TKI inhibitors to the combination regimen in order for maximum downregulation of VEGF/VEGFR." (PMID 30380599, 2018). "It is also not clear whether Nrf2 expression—like HIF-1α expression—is different in peripheral lymphoid organs and tumor MDSCs and whether it might therefore also influence local MDSC maintenance." (PMID 30425715, 2018). "Indeed, in our study, we identified that anti-tumor role of Sal-B might be partially contributed by productive modulation of MMP, ROS level, and cellular apoptosis via inhibiting HIF-1α signaling pathway." (PMID 29789538, 2018). "Thus, detection of HIF-1α and GLUT-1 activity may accurately reflect metabolic ability of tumors or tumor cells." (PMID 30546057, 2018). "Importantly, these tumor cells lack expression of HIF-1α and are thus not hypoxic but instead express several markers associated with an immature neural crest-like phenotype." (PMID 29032465, 2018). "Besides that, serum levels of HIF-1α were also significantly higher in patients with tumor metastasis than in patients without metastasis (P<0.05)." (PMID 29899167, 2018). "Interestingly, HPV16 oncoproteins seem to contribute to non-small cell lung cancer (NSCLC) progression by promoting hypoxia-inducible factor 1-alpha (HIF-1α)/VEGF-mediated tumor angiogenesis and by enhancing EMT through the activation of PI3K/Akt/HIF-1α signaling." (PMID 30563114, 2018). "Indeed, the tumor Pi-ATAC data demonstrate a significant increase of DNA accessibility of motifs for Fox family and E2f3 in the cells with high HIF1α protein (Wilcoxon test p < 0.05) in a more detailed comparison of TF motif accessibility across the three groups." (PMID 30389926, 2018). "HIF-1α is one of the most important transcription factors for controlling many hypoxia-inducible genes, and accumulating evidence suggests that hypoxia-inducible factor-1α (HIF-1α) mediates tumor metabolic responses and promotes tumor proliferation, angiogenesis, and metastasis." (PMID 29614836, 2018). "Activated VEGF signaling in ccRCC due to increased HIF-1α activity may enhance lipoprotein uptake into the tumor not only by direct actions on tumor cells but also by indirectly promoting their transport from the circulation into the tumor tissue." (PMID 30173145, 2018). "Besides that, serum levels of HIF-1α were also significantly higher in patients with tumor metastasis than in patients without metastasis." (PMID 29899167, 2018). "Under hypoxic stress, induction and stabilization of HIF-1α and/or HIF-2α lead to upregulation of transcription of numerous hypoxia-responsive genes related to metabolic and immune pathways, and resulting in modulation of both metabolism and immunity of tumor and stromal cells." (PMID 30061885, 2018).
tumor (continued). "Additionally, tumor 3D spheroids cultured with CPAP monocytes showed an antitumor immune response similar to that of monocytes from healthy donors, which corroborates the crucial role of HIF1α and VEGF in OSA monocytes." (PMID 29997451, 2018). "Moreover, Kaplan–Meier analysis showed that high expression of HIF-2α, rather than HIF-1α, in tumor tissues predicted an unfavorable postoperative prognosis." (PMID 29357946, 2018). "Moreover, recent literature illustrated that HIF-2α, rather than HIF-1α, was the main tumor inducer in ccRCC." (PMID 28903320, 2017). "In addition, expression level of cleaved caspase-3 protein was increased and the reduced levels of HIF-1α and VEGF expressions were observed after the treatment of TFAE, suggesting the antitumor effect of TFAE by trigging apoptosis and inhibition of tumor angiogenesis." (PMID 29348766, 2017). "Together with the evidence of upregulation of HIF-1α mRNA in ALK-positive anaplastic large cell lymphoma under normoxic condition, we therefore hypothesized that ALK signaling may contribute to tumor growth through hypoxia-independent neovascularization in GBMs." (PMID 28837676, 2017). "In the tumor tissues, OL reduced HFD-induced expression of angiogenesis (CD31, VE-cadherin, VEGF-A, and VEGFR2), lymphangiogenesis (LYVE-1, VEGF-C, VEGF-D, and VEGFR3), and hypoxia (HIF-1α and GLUT-1) markers as well as HFD-induced increases in lipid vacuoles and M2 macrophages (MΦs)." (PMID 28410190, 2017). "Similarly, in CAKI-1 tumor xenografts, tumor regions that stained positive for HIF-1α had no or little phospho-S6 staining (Ser 235/236)." (PMID 28280521, 2017). "We show a decreased ratio of IFNγ+ to FOXP3+ cells in CD4+ TILs lacking HIF-1α, which could further contribute to the observed accelerated tumor growth." (PMID 29136509, 2017). "Thus, it is speculated that HIF-1α may stimulate angiogenesis by increasing the expression of VEGF to adapt to the growth environment of hypoxic and low-sugar content, so that the tumor can continue to grow and metastasize distantly." (PMID 29267502, 2017). "We found that HIF1-α could induce EMT, which can contribute to tumor cell plasticity." (PMID 28449718, 2017). "In this study, we found that Ang II promotes HIF-1α expression in hypoxic tumor cells and that Ang II signal-blocking abrogates hypoxia-induced HIF-1α expression, indicating a crucial role for the local RAS in intracellular accumulation of HIF-1α protein in the hypoxic tumor microenvironment." (PMID 28205588, 2017). "HIF-2α has often been studied in human tumor cell lines and human cells without functional HIF-1α." (PMID 27699500, 2017). "In addition, hypoxia promotes PDGFR-induced autophagy in tumor cells dependent on HIF-1α signaling while independent of BNIP3 and BNIP3L." (PMID 28729825, 2017). "When time to recurrence was introduced, in addition to age, tumor size, HPV status, and disease stage, in multivariate models to assess whether HIF-1α +/− CAIX over-expression has an independent prognostic meaning, statistical significance was lost (HR: 1.22, 95% CI: 0.88–1.7, p = 0.223)." (PMID 28099149, 2017). "Consequently, this led to attenuated transactivation of HIF-1 target genes under hypoxia, as exemplified by reduced glut-1 and vegf transcription in 64B-treated tumor cells without affecting HIF-1α mRNA level." (PMID 29245898, 2017). "The HIF-1α expression was seen to be accumulated in the tumour mass specifically in the UT-SCC-14 xenografts, which might be due to the hypoxic condition present in the tumour mass." (PMID 28756482, 2017). "Therefore, ROS elevation above a threshold level may increase the stability of HIF-1α, thereby augmenting HIF-1-dependent adaptation responses to hypoxia, and contribute to tumor progression under IH-2 conditions." (PMID 28977888, 2017).